INS (insulin)
Diseases named in the same sentence as INS in open-access papers (continued):
Sharing a sentence is not in itself a finding about the gene and the disease.
type 1 diabetes (continued). "The specific aim was to establish the effect of the C-peptide concentration on the prevalence of CSBH in pregnant women with type 1 diabetes and its association with insulin dosage." (PMID 35207323, 2022). "An alternate strategy to counter insulin deficiency in type 1 diabetes is beta cell replacement therapy, which involves replacing dysfunctional or damaged beta cells with healthy insulin-secreting beta cells." (PMID 36351917, 2022). "A high GADA level in LADA has been associated with earlier insulin initiation, lower BMI and type 1 diabetes-associated genes, for example, being more type 1 diabetes-like both phenotypically and genotypically." (PMID 35616612, 2022). "Type 1 diabetes (T1D) is a chronic autoimmune disease caused by the destruction of insulin-producing beta cells in the pancreas." (PMID 36384715, 2022). "T2DM has been commonly known as a non-insulin-dependent condition, in contrast to diabetes type 1 in which an absolute insulin deficiency is produced, associated with autoimmune destruction of the pancreatic β cells." (PMID 36009573, 2022). "Type 1 diabetes (T1D), sometimes referred to as juvenile diabetes, is caused by the destruction of pancreatic beta cells resulting in insufficient amount of insulin and hence elevated blood sugar levels." (PMID 34659260, 2021). "Type 1 diabetes (T1D) arises from local pancreatic islet inflammation that contributes to the progressive loss of insulin-secreting β-cells." (PMID 33578952, 2021). "This gene encodes a major islet autoantigen in type-1 diabetes and plays an important role in insulin secretion in response to glucose stimuli and β-cell transcription and proliferation." (PMID 35052758, 2021). "Type 1 diabetes (T1D) is caused by autoimmune destruction of beta cells, resulting in loss of functional secreted insulin levels that leads to constantly elevated blood glucose." (PMID 33667022, 2021). "Type 1 diabetes is a lifelong, incurable condition characterized by a deficiency of insulin caused by immune-mediated destruction of pancreatic beta-cells in genetically predisposed individuals." (PMID 33996702, 2021). "This study found that the use of insulin pumps was associated with a lower likelihood of developing DR among patients with type 1 diabetes." (PMID 34570208, 2021). "We mainly focused on type 1 diabetes, meaning a total loss of insulin due to destruction of pancreatic β-cells by streptozotocin." (PMID 34445586, 2021). "For example, early-onset type 1 diabetes is associated with the presence of other autoimmune diseases, higher insulin antibodies value, lower initial insulin reservoir, and higher insulin requirements 1 year after diagnosis." (PMID 35096943, 2021). "Type 1 diabetes (T1D) is a tissue-specific autoimmune disease caused by the autoreactive T cell–mediated destruction of insulin-producing β-cells in the pancreas." (PMID 33732229, 2021). "In the ITN AbATE study, treatment with teplizumab delayed the loss of residual insulin secretion in patients with type 1 diabetes in a subset of subjects, with some maintaining insulin secretory function for several years." (PMID 34616405, 2021). "Insulin is a major autoantigen in type 1 diabetes and insulin autoantibodies are one of five islet autoantibodies used by Type 1 Diabetes TrialNet to identify individuals at high risk for type 1 diabetes." (PMID 34234784, 2021). "T- and B-lymphocytes play an important role in the pathogenesis of type 1 diabetes (T1D), a chronic disease caused by the autoimmune destruction of the insulin-producing cells in the pancreatic islets." (PMID 34938295, 2021). "Type 1 diabetes is characterized by immune-mediated destruction of pancreatic β-cells, causing lifelong dependency on exogenous insulin." (PMID 34881246, 2021). "Type 1 diabetes (T1D) is characterised by autoimmune‐mediated destruction of pancreatic beta‐cells and loss of glucose‐stimulated insulin responses leading to chronic hyperglycaemia." (PMID 34267894, 2021).
type 1 diabetes (continued). "Type 1 diabetes arises from the autoimmune-induced loss of insulin producing pancreatic cells, with ≈70% loss at clinical presentation." (PMID 34083567, 2021). "Clinically, a higher level of serum cystatin C was associated with decreased insulin sensitivity in type 1 diabetic patients." (PMID 34899825, 2021). "The alteration in sphingolipids are likely secondary effects to a mutation in INS, the gene encoding insulin, and responsible for triggering type 1 diabetes." (PMID 34071409, 2021). "In the present study, we investigated the number of hospital days per person-year between 2009 and 2018 associated with the use of insulin pump therapy vs. injection therapy in 48,756 pediatric patients with type 1 diabetes in Germany." (PMID 33258970, 2021). "Invasion of pancreatic islets by immune cells is a hallmark of Type 1 Diabetes (T1D), where the innate and adaptive immune systems work cooperatively to mediate damage of insulin- secreting β cells." (PMID 34163475, 2021). "Loss of pancreatic β cells is the hallmark of type 1 diabetes, for which provision of insulin is the standard of care." (PMID 34302056, 2021). "If a component of the ‘IR syndrome’ is caused solely by deficient insulin action, then it should be seen in undertreated type 1 diabetes." (PMID 34841432, 2021). "Type 1 diabetes (T1D) is mostly a juvenile-onset disease due to autoimmune destruction of pancreatic beta cells, leading to an absolute deficiency in insulin production." (PMID 34830246, 2021). "As concluded in a previous review, insulin resistance to exogenous insulin is deteriorating over the course of type 1 diabetes, which was found to be associated to some extent to bodyweight." (PMID 34295305, 2021). "Studies in young individuals with type 1 diabetes demonstrate increased blood lipids, which can be due to insufficient insulin treatment since poor glycaemic control is associated with dyslipidaemia." (PMID 33283333, 2021). "Type 1 diabetes (T1D) is caused by loss of immune tolerance to insulin-producing beta cells in the pancreas." (PMID 33992646, 2021). "Type 1 diabetes is characterized by the loss of insulin-producing ß-cells in pancreatic islets of Langerhans leading to insulin shortage." (PMID 33912139, 2021). "Type 1 diabetes (T1D) is caused by immune mediated loss of insulin producing beta cells, resulting in a life-long intrinsic inability to maintain glucose homeostasis." (PMID 33808310, 2021). "Even with intensive insulin therapy, individuals with type 1 diabetes are at risk of acute complications such as hypoglycaemia and ketoacidosis, and of long-term microvascular and macrovascular complications." (PMID 33145642, 2021). "Type 1 diabetes (T1D) is an organ-specific autoimmune disease, whereby immune cell-mediated killing leads to loss of the insulin-producing β cells in the pancreas." (PMID 34529725, 2021). "Type 1 diabetes is an organ-specific autoimmune disease caused by the selective destruction of insulin-producing β cells located in pancreatic islets of Langerhans." (PMID 33690220, 2021). "Type 1 Diabetes (T1D) is an autoimmune disease caused by the selective destruction of insulin-producing pancreatic beta cells, resulting in persistent hyperglycemia." (PMID 34122410, 2021). "Insulin pump therapy in type 1 diabetes is associated with improvement in hemoglobin A1C (HbA1C) and reduction in episodes of severe hypoglycemia and diabetic ketoacidosis (DKA)." (PMID 34064129, 2021). "Type 1 diabetes mellitus (T1DM) is a chronic autoimmune disease caused by destruction of the insulin-producing pancreatic beta cells." (PMID 34283897, 2021). "Beyond insulin, other drugs have been proposed for the management of type 1 diabetes, in association with insulin." (PMID 33755854, 2021). "Type 1 diabetes is caused by the destruction of insulin-producing beta cells in the pancreas leading to insulin deficiency and lifelong dependency on daily insulin therapy." (PMID 34390364, 2021).
type 1 diabetes (continued). "Type 1 diabetes is regarded as absolute deficiency of insulin and is attributed to the complete damage of islet β cells." (PMID 34307690, 2021). "Autoimmune destruction of pancreatic β-cells results in the permanent loss of insulin production in type 1 diabetes (T1D)." (PMID 34759828, 2021). "For example, ex vivo detection of anti-insulin B cells is challenging in both humans and mice at high risk for type 1 diabetes, despite being seropositive for insulin autoantibody." (PMID 34234784, 2021). "Type 1 diabetes is a chronic disease of the pancreas characterized by the loss of insulin-producing beta cells." (PMID 34179094, 2021). "Type 1 diabetes is an autoimmune disease caused by T cell-mediated destruction of insulin-producing β cells." (PMID 34394099, 2021). "G-protein-coupled receptor signaling pathways are related with the crosstalk with insulin signaling, while chemokines have been found to be associated with or implicated in the pathogenesis of type 1 diabetes." (PMID 34361788, 2021). "Type 1 diabetes is mostly induced by autoimmune diseases causing the destruction of the pancreatic β-cells responsible of the insulin production." (PMID 34959301, 2021). "In patients with inadequately controlled type 1 diabetes, dapagliflozin treatment was associated with significantly decreased HbA1c, body weight, total insulin dose and glycemic variability." (PMID 34394274, 2021). "Type 1 diabetes is a condition caused by autoimmune damage to the insulin-producing β-cells of the pancreatic islets, usually leading to severe endogenous insulin deficiency." (PMID 34959363, 2021). "Type 1 diabetes (T1D) is considered to be caused by an autoimmune T cell–mediated destruction of insulin-producing beta cells in the pancreas leading to loss of glucose homeostasis." (PMID 32833039, 2021). "Most notable among these are changes in intraislet insulin that stems from loss of β‐cells and peripheral administration of insulin in patients with type 1 diabetes." (PMID 33855225, 2021). "Type 1 diabetes (T1D) is an autoimmune disease that culminates in beta cell destruction in the pancreas and, subsequently, deficiency in insulin production." (PMID 33604389, 2021). "Type 1 diabetes (T1D) is an organ-specific disease characterized by the deficiency of insulin caused by the autoimmune destruction of pancreatic islet β cells." (PMID 35095751, 2021). "Type 1 diabetes (T1D) is characterised by absolute insulin deficiency, requiring insulin to be injected subcutaneously several times a day." (PMID 33462097, 2021). "Type 1 diabetes (T1D) is also a chronic autoimmune disease, precipitated by destruction of insulin-producing pancreatic cells, leading to insulin deficiency." (PMID 34183004, 2021). "In type I diabetes mellitus, there is a significant insulin deficiency and the only therapeutic option is the administration of insulin or insulin analog." (PMID 34077431, 2021). "The classical view of type 1 diabetes assumes that the autoimmune mediated targeting of insulin producing ß-cells is caused by an error of the immune system." (PMID 33912139, 2021). "Type I diabetes refers to immune-mediated beta-cell destruction that causes endogenous insulin depletion, while type II involves insulin secretion defects and/or insulin resistance." (PMID 34117315, 2021). "Type 1 diabetes mellitus (T1DM) is a chronic disease characterized by deficiency in insulin production due to the loss of pancreatic β cells, with consequent hyperglycemia." (PMID 34614139, 2021). "The plasma circulating miR-23b-3p at disease onset is associated with reduced insulin secretion in patients with type 1 diabetes." (PMID 33781239, 2021). "Type 1 diabetes, which mostly occurs in young children, is caused by a pancreas disorder where insulin production cannot meet the body’s demand." (PMID 33800659, 2021). "Type 1 diabetes (T1D) is characterized by an absolute deficiency of insulin secretion with hyperglycemia as a consequence." (PMID 34458264, 2021).
type 1 diabetes (continued). "In type 1 diabetes (T1D), autoreactive immune cells infiltrate into the pancreatic islets resulting in loss of insulin-producing beta cells and ultimately leading to hyperglycemia." (PMID 33918805, 2021). "Type 1 diabetes is caused by an autoimmune reaction where the body’s immune system attacks the insulin-producing beta cells in the islets of the pancreas gland." (PMID 33413645, 2021). "Type 1 diabetes (T1D) is an autoimmune disorder characterized by impaired blood sugar control and insulin deficiency due to an autoimmune destruction of insulin-producing cells in the pancreas." (PMID 35095751, 2021). "Type 1 diabetes (T1D) is an autoimmune disease that causes destruction of insulin-producing beta cells of pancreas." (PMID 33419247, 2020). "Loss of the glucagon counter-regulatory response to hypoglycaemia occurs in many individuals with type 1 diabetes within 5 years of diagnosis and is linked, in part, to the loss of a paracrine effect of endogenous insulin on alpha cells in pancreatic islets." (PMID 32034440, 2020). "Type 1 Diabetes (T1D) is a T cell-mediated autoimmune disorder caused by the destruction of insulin-secreting cells." (PMID 32787907, 2020). "Diabetes is caused by dysfunction of insulin production, leading to hyperglycemia, and typically includes type 1 diabetes and type 2 diabetes." (PMID 33066521, 2020). "Type 1 diabetes (T1D) is characterized by an irreversible impairment of glucose homeostasis due to the loss of insulin-producing pancreatic beta cells." (PMID 32664675, 2020). "A preferential loss of capacity for insulin release in response to low glucose concentrations was observed at debut of type 1 diabetes." (PMID 32618430, 2020). "OVE26 mice are transgenic animals that elicit calmodulin overexpression in pancreatic β-cells, insulin production deficiency, and type I diabetes." (PMID 32566684, 2020). "Autoimmunity is thought to cause type 1 diabetes that leads to insufficient production of insulin by pancreatic beta cells." (PMID 32676275, 2020). "In conclusion, women with GDM, especially those on insulin treatment, should be carefully monitored for the first decade after the pregnancy, after which the risk for type 1 diabetes becomes negligible." (PMID 32725280, 2020). "Type 1 diabetes (T1DM) is characterized by a deficient insulin production caused by T-cell-mediated autoimmune destruction of pancreatic β-cells." (PMID 32708413, 2020). "Type 1 diabetes (T1D) results from autoimmune destruction of insulin-producing beta-cells in the pancreas, caused by the interplay of genetic and environmental factors." (PMID 32872668, 2020). "Approximately 25% of people with type 1 diabetes have suppressed counterregulatory hormonal and symptomatic responses to insulin-induced hypoglycaemia, which renders them at increased risk of severe, disabling hypoglycaemia." (PMID 31942669, 2020). "Type 1 diabetes (T1D) is a metabolic disease caused by the autoimmune destruction of the insulin-producing pancreatic β-cells." (PMID 33144616, 2020). "Patients were taught only survival skills associated with the management of type 1 diabetes (ie, blood glucose level monitoring, carbohydrate counting and dosing, long-acting insulin administration, and hypoglycemia and ketone corrections)." (PMID 32125428, 2020). "In streptozotocin-treated mice, which is a rodent model for insulin deficient type 1 diabetes, high glucose increased the expression of renal CCL2 and CCL5, which was associated with the induction of diabetic nephropathy." (PMID 33207809, 2020). "In the current study, we used an STZ model, which is one of the most common models to investigate complications associated with insulin deficient type 1 diabetes." (PMID 32903422, 2020). "Type 1 diabetes (T1D) is an autoimmune disease caused by the destruction of the insulin-producing β-cells." (PMID 33569058, 2020).
type 1 diabetes (continued). "Type 1 diabetes is an autoimmune disease characterised by a loss of functional insulin-producing beta cells in the pancreas." (PMID 31754749, 2020). "In type 1 diabetes (T1D), the cause is an absolute deficiency of insulin secretion due to an autoimmune-mediated response." (PMID 33147748, 2020). "Insulin dose has been found to associate to several cardiometabolic risk factors in type 1 diabetes." (PMID 33370380, 2020). "Type 1 diabetes is caused by autoimmunity against insulin-producing β-cells in pancreatic islets of Langerhans." (PMID 32887316, 2020). "Type 1 diabetes (T1D) is a chronic metabolic condition caused by the autoimmune destruction of pancreas beta-cells which are responsible for insulin production." (PMID 32664432, 2020). "There is a loss of insulin secretion resulting in insulin deficiency associated with type 1 diabetes." (PMID 32676275, 2020). "Type 1 diabetes is the result of loss of pancreatic beta cells due to the autoimmune destruction, and type 2 is defective in insulin-sensing cells as well as beta cell death." (PMID 32397116, 2020). "Underlining the trophic effects of insulin on acinar cells, acinar atrophy was most pronounced around insulin-deficient islets compared with insulin expressing islets in autopsies of patients with type 1 diabetes." (PMID 32239341, 2020). "Type 1 diabetes (T1D) is a severe form of the disease and is often referred to as juvenile diabetes or “insulin-dependent diabetes” which is the result of loss of insulin-hormone producing islet cells in the pancreas which normally promotes glucose metabolism." (PMID 32968716, 2020). "The risk for type 1 diabetes is strongly associated with HLA-DQ and the appearance of beta cell autoantibodies against either insulin, glutamate decarboxylase (GAD65), insulinoma-associated protein-2 (IA-2), or zinc transporter 8 (ZnT8)." (PMID 32743532, 2020). "Type 1 diabetes (T1D) is caused by the destruction of pancreatic islet beta cells resulting in total loss of insulin production." (PMID 33033923, 2020). "Type 1 diabetes is an autoimmune disease caused by the destruction of the insulin-producing β-cells." (PMID 32477262, 2020). "The rate of beta cell damage and insulin loss in type 1 diabetes seems to be associated with more susceptible genotypes and the influence of undefined environmental factors." (PMID 31990164, 2020). "Type 1 diabetes is associated with malfunction of the pancreatic islets and more specifically with the destruction of the insulin-producing cells (beta cells), which reside inside the islets." (PMID 32766229, 2020). "In type 1 diabetes, the lowest quartile of normalized callosal area was associated with higher insulin doses (p = 0.029) and reduced insulin sensitivity (p = 0.033)." (PMID 32063882, 2020). "Type 1 diabetes (T1DM) is an autoimmune disease caused by antibody-mediated destruction of insulin producing beta cells in pancreatic islets of Langerhans that usually manifests during childhood or adolescence and persists lifelong." (PMID 33425916, 2020). "Neo-islets have also been reported in human pancreas, including those from patients with type 1 diabetes, but this is the first demonstration of insulin+ cells with a ductal origin caused by liraglutide." (PMID 32477262, 2020). "Type 1 diabetes (T1D) is an autoimmune disease characterized by T cell–mediated destruction of the insulin-secreting beta cells, resulting in insulin deficiency and hyperglycemia." (PMID 31900603, 2020). "Type 1 diabetes (T1D), called insulin-dependent diabetes, is characterized by the loss of the ability of beta cells to produce insulin." (PMID 32615920, 2020). "Recently, it has been reported an association between insulin dose and several cardiometabolic risk factors in type 1 diabetes." (PMID 33370380, 2020). "Type-1 diabetes (T1D) is an autoimmune disease caused by progressive loss of insulin-producing beta cells in the pancreas." (PMID 33154424, 2020).